ZFX (zinc finger protein X-linked)
Diseases named in the same sentence as ZFX in open-access papers (continued):
Sharing a sentence is not in itself a finding about the gene and the disease.
cancer (continued). "It is suggested that different ZFX isoforms may have different expressions and functions in cancer cells." (PMID 29753316, 2019). "In addition to the elevated levels of ZFX in human cancers, overexpression of ZFX is also observed in pluripotent embryonic stem cells (ESCs) and hematopoietic stem cells (HSCs)." (PMID 28156061, 2017). "Indeed, several studies have demonstrated the contribution of ZFX in the maintenance of stem cell‐like characteristics in multiple cancer types." (PMID 28156061, 2017). "A thorough and comprehensive analysis about ZFX in different cancers are also needed, and such analysis will help to clarify the distinct and overlapping roles of ZFX in different cancers, paving the way for the development of efficient clinical applications targeting ZFX." (PMID 25916205, 2015). "Though ZFX dysfunctions have been identified in variant human diseases and especially in cancers, its pathological roles have not been fully addressed." (PMID 25916205, 2015). "In addition, ZFX silence induced apoptosis as characterized by the prominent presence of sub-G1 apoptotic cancer cells." (PMID 24353675, 2013). "Moreover, ZFX silencing reduces the transactivation of β-catenin in liver EpCAM+ cancer stem cells; however, the detailed mechanism remains unclear." (PMID 37864206, 2023). "In addition, high ZFX expression correlates with poor survival of cancer patients." (PMID 29429977, 2018). "Because tumor cells require abnormally high levels of transcription for their inappropriate proliferation and survival, increased overall transcription mediated by ZFX may explain why this TF has been correlated with poor prognosis for a variety of human cancers." (PMID 29429977, 2018). "On a pan-cancer scale, we replicated prior findings of sex-chromosome dosage-dependent gene essentiality in the DepMap CRISPR knockout screen in DDX3X, EIF1AX, ZFX and MAGEH117." (PMID 39975298, 2025). "Further, we showed that RICTOR regulates three transcription factors, like ZFX, CTCF, and ELF1, that can further regulate multiple genes/enzymes, including some from the sphingolipid and ganglioside pathways in a cell-type and cancer-context-dependent manner." (PMID 40934285, 2025). "While RICTOR and ZFX showed similar expression in both normal and cancerous epithelial cells, UGCG expression was elevated in cancer cells compared to normal epithelial cells." (PMID 40934285, 2025). "Injury-induced populations were highest for TFs related to cell proliferation, self-renewal, and cancer involving both intrinsic (E2F family, MYC, and ZFX) and extrinsic (HIF1a, EPAS1/HIF2a, NFYB, LEF1, GLI2, VDR, and SMAD1/3/5) pathways." (PMID 38905342, 2024). "Particularly, expressions of ZFX and TXLNG were both positively correlated with XIST in over 10 cancers." (PMID 36212008, 2022). "Here, we unraveled that ZFX expression increased significantly in tongue SCC tumors, another type of cancer of HNSCC, as compared to tumor-adjacent normal tissues." (PMID 25916205, 2015). "In addition, ZFX preferably binds promoters of oncogenes containing CpG islands like SPRY4 and is considered a transcriptional activator in many cancer cells." (PMID 36384366, 2023). "Nontypical examples included ZFX, a self-renewal TF, which is highly expressed in tumors and binds across the genome to thousands of CpG island promoters, many of which regulate cell cycle and cancer-related genes." (PMID 38905342, 2024).
tumor (24 papers, 2013 to 2025). "Zinc finger protein X-linked (ZFX) has been shown to promote the growth of tumor cells, including leukemic cells." (PMID 37864206, 2023). "Zinc finger protein, X-linked (ZFX), as a member of the highly-conserved zinc finger protein Zfy family, is intimately involved in tumor metastases." (PMID 33046994, 2020). "Somatic mutations in ZFX codons 786 and 787 were identified by exome sequencing in two tumor samples." (PMID 25594030, 2014). "Only the ZFX gene was mutated in more than one tumor and in neighboring codons suggestive of a mutational hotspot prompting further investigation." (PMID 25594030, 2014). "In contrast, the ZFX variant 5 was down-regulated in tumor tissues." (PMID 29753316, 2019). "The ZFX mutations we identified were strikingly specific, focused in each tumor on one encoded residue in a hotspot of two consecutive highly conserved arginine residues (R786/787; arginine to glutamine, threonine or leucine) in a zinc finger domain near the C-terminus of the protein." (PMID 25594030, 2014). "This study provides the first genetic evidence of recurrent ZFX mutations in human neoplasia." (PMID 25594030, 2014). "Hence, ZFX-spliced transcripts may be considered as novel tumor markers with potential diagnostic, prognostic, and therapeutic values." (PMID 29753316, 2019). "Until now, pathogenetic importance could not be attributed to this isolated finding, but in the context of our current observations, the listing of this mutation in a different tumor type suggests that recurrent R786/787 mutations in ZFX may contribute to human tumorigenesis in a broader fashion." (PMID 25594030, 2014). "The key to understanding how ZFX regulates tumor cells is to identify the direct transcriptional targets of ZFX." (PMID 37864206, 2023). "Considering that ZFX silencing inhibited the growth of CML cells, our data indicated that ZFX facilitates leukemogenesis induced by BCR/ABL similar to its role in other tumor models induced by different oncoproteins, such as Hedgehog or MLL–AF9." (PMID 37864206, 2023). "Overall, ZFX upregulation is a poor prognostic marker, and ZFX silencing inhibits the growth of tumor cells and sensitizes them to chemotherapy." (PMID 37864206, 2023). "Considering the relationship between stem cell and tumor characteristics, the role of ZFX in tumors has received increasing research attention." (PMID 32760226, 2020). "Overexpression of ZFX reversed the tumor-suppressive effects of miR-218 on TNBC cell proliferation, migration, and invasion." (PMID 31310241, 2019). "The upregulation of ZFX in HCC samples was significantly associated with multiple malignant clinicopathological features of HCC, such as tumor size, tumor number, and tumor differentiation grade." (PMID 28156061, 2017). "In contrast, hypomethylation was enriched in motifs of transcription activator binding genes, such as ETS, ZFX, cMYC, which are again involved in cell growth, apoptosis, and metabolism, processes necessary for tumor progression." (PMID 27461342, 2016). "In this study, we examined the correlation between ZFX expression and the clinical characteristics of stage II/III CRC patients, as well as the molecular mechanism by which ZFX apparently contributes to CRC tumor progression." (PMID 26967242, 2016). "ZFX was over-expressed in various tumor tissues compared to healthy tissues and had important effect on tumor proliferation and metastasis." (PMID 25617627, 2015). "We found that ZFX expression was significantly higher in tongue SCC tumors as compared to tumor-adjacent normal tissues." (PMID 25916205, 2015). "Results showed that ZFX expression in tumor tissues was significantly higher than that in adjacent normal tissues." (PMID 25916205, 2015). "Then, ZFX expression status was examined using immunohistochemistry (IHC) staining in tumor and adjacent normal tissues (representative images)." (PMID 25916205, 2015).
tumor (continued). "In terms of NSCLC, it seems that the anti-tumor activity of mir-144 is at least partially through turning down ZFX protein expression at a post-transcription level." (PMID 24066116, 2013). "A few reports showed that ZFX serves as a target for mir-144 and exerts regulatory effects on tumor growth." (PMID 24066116, 2013). "Consistent with the previous data, ELISA showed the relative expression levels of ZFX in normal (n = 26) were significantly lower than that in tumor tissues (n = 26, p<0.001)." (PMID 24066116, 2013). "Among them, ERG, ZFX and SOX2 have been reported to be highly associated with tumor development." (PMID 38389573, 2024). "ZFX was reported to be binding at CpG island promoters in many tumor cell types." (PMID 34292930, 2021). "In addition, reduced expression of miR-144 in NSCLC promote tumor cells proliferation and inhibits apoptosis via upregulating zinc finger X-chromosomal protein (ZFX)." (PMID 32316322, 2020). "While the expressions of ZFX variant 1/3 and ZFX variant 4 were elevated in tumor vs. non-tumor breast samples, the expression of ZFX variant 5 had reverse result." (PMID 29753316, 2019). "The expression of ZFX variant 5 was down-regulated in tumor tissues in comparison to marginal non-tumor samples, but ZFX variant 5 was expressed more strongly in low-grade tumors compared to high-grade tumors (p < 0.01)." (PMID 29753316, 2019). "In a xenograft model, ZFX knockdown suppressed in vivo CRC tumor growth." (PMID 26967242, 2016). "To test whether ZFX also exerts direct regulatory function on NSCLC tumor growth, we knocked down ZFX protein in A549 cells." (PMID 24066116, 2013). "In particular, we observed no mutations that would be expected to inactivate the ZFX gene product, such as early stop codons or frameshifts; in addition, none of the female patients' tumor samples that harbored a ZFX mutation showed LOH at the corresponding wild type locus." (PMID 25594030, 2014). "Our study, on the other hand, unraveled and validated that ZFX, a key C2H2-type, ZNF family transcription factor, mediates UGCG expression and thereby modulates sphingolipid and ganglioside metabolism and tumor progression." (PMID 40934285, 2025). "We further demonstrate that elevated expression of ZFX/UGCG alters ganglioside levels and activates epidermal growth factor receptor (EGFR)-mediated PI3K/AKT/mTOR/MAPK signaling, leading to tumor progression." (PMID 40934285, 2025). "Metadata analysis further confirmed that luminal A and luminal B tumor tissues have higher UGCG and ZFX expression over other subtypes as observed in the TCGA data set, and expression of UGCG and ZFX is also high in ER+ and PR+ tumor tissues." (PMID 40934285, 2025). "We further demonstrate that RICTOR regulates the synthesis of GD3 gangliosides through ZFX and UGCG, and triggers the activation of the EGFR signaling pathway, thereby promoting tumor growth." (PMID 40934285, 2025). "Differential gene expression data analysis showed that luminal A and B tumor tissues have significantly higher expression of UGCG and ZFX than basal and HER2+ groups." (PMID 40934285, 2025). "ZFX expression was higher in TNBC than normal breast cell lines and higher in TNBC tumor tissue than adjacent normal breast tissue." (PMID 31310241, 2019). "Using immunohistochemistry, we detected expression of ZFX in CRC tissues collected from stage II/III patients and determined that its expression correlated with tumor differentiation and stage." (PMID 26967242, 2016). "In this study, we detected high ZFX expression in a majority of stage II/III CRC tissue samples tested, which correlated with tumor differentiation and stage along with its involvement in the CRC development." (PMID 26967242, 2016).
tumor (continued). "Finally, we quantified the expression of UGCG and ZFX from luminal tumors by qRT-PCR, and observed ~2-fold increase in the expression of ZFX and UGCG in tumor tissues over adjacent matched normal control." (PMID 40934285, 2025). "Finally, Indian patient tumor tissues with high RICTOR expression also manifest high UGCG and ZFX expression, emphasizing the role of mTORC2-regulated ganglioside metabolism in tumor development." (PMID 40934285, 2025). "Furthermore, this panel revealed the potential colocalization of multiple tumor cell markers such as β-catenin, ADAM10, ZFX, and ZEB2." (PMID 34490110, 2021). "Studies also showed that miR-144 overexpression could inhibit the tumor growth and induce cell apoptosis in NSCLC which is in accordance with the effect of ZFX knockdown." (PMID 25916205, 2015). "As expected, we found that ZFX knockdown strongly induces NSCLC apoptosis (as manifested by enhanced apoptotic protein markers and flowcytometry) and suppresses tumor cell growth, which is similar to the biological effects we observed for mir-144 over-expression shown in previous figures." (PMID 24066116, 2013). "Additionally, in gastric cancer FTX exerts a similar functional role via the miR-144/ZFX and miR-215-3p/SIVA1 regulatory axis in promoting tumorigenesis; in addition, FTX was upregulated in tumor tissues in comparison to adjacent non-tumor tissues and correlated to poor prognosis." (PMID 35054794, 2022).
infection (1 paper, 2013). The state of being infected such as from the introduction of a foreign agent such as serum, vaccine, antigenic substance or organism. "The expression of ZFX protein was significantly decreased after infection." (PMID 24353675, 2013).
ZFX also shares sentences with these, for which no sentence is quoted: non-small cell lung carcinoma (5 papers); malignant glioma (2); benign prostatic hyperplasia (1); bladder cancer (1); coronary heart disease (1); embryonic carcinoma (1); hyperparathyroidism (1); Infertility (1); Intellectual disability (1); invasive breast carcinoma (1); oral squamous cell carcinoma (1); parathyroid tumor (1); premature ovarian failure (1); schizophrenia (1); urothelial bladder cancer (1).